FAP (fibroblast activation protein alpha)
Diseases named in the same sentence as FAP in open-access papers (continued):
Sharing a sentence is not in itself a finding about the gene and the disease.
mesothelioma (29 papers, 2013 to 2025). A usually malignant and aggressive neoplasm of the mesothelium which is often associated with exposure to asbestos. "For many years, FAP has been recognised as a promising immunotherapy target for carcinomas and mesothelioma." (PMID 38975278, 2024). "in a mesothelioma xenograft model with tumor cell FAP expression and was further determined to be safely tolerated in a phase I clinical trial of autologous FAP(hF1) CAR T-cells against malignant pleural mesothelioma (MPM)." (PMID 37251405, 2023). "Previous studies report that FAP-targeted CAR-T cells decreased FAP-positive stromal cells in mouse mesothelioma and lung models." (PMID 37046312, 2023). "Finally, as fibrosis is a major cause of morbidity in mesothelioma patients, we investigated whether vistusertib, saracatinib and cediranib could inhibit the activation state (expression of αSMA and FAP) or the productive phenotype (expression of FN) of fibroblasts." (PMID 37938546, 2023). "The authors found that the redirected T cells successfully lysed FAP+ mesothelioma cells in an antigen-specific manner in vitro and in vivo." (PMID 35211124, 2022). "There has been one reported clinical trial in which FAP CAR-T cells have been locally injected into the pleural effusion of mesothelioma patients (NCT01722149)." (PMID 32625204, 2020). "Schuberth and colleagues developed an intra-peritoneal model for the adoptive transfer of FAP-CARs in a mesothelioma xenograft." (PMID 28331617, 2017). "As expected from FAP positive IHC of MPM specimens the mesothelioma derived cell line MSTO-211H showed FAP expression." (PMID 23937772, 2013). "In those studies, FAP has primarily been investigated as the target of tumor‐supporting stroma, but can also serve as a direct tumor target in certain cancers such as mesothelioma." (PMID 38975278, 2024). "More than 40% of pancreatic, cancer of unknown primary (CUP), salivary gland and mesothelioma tumors highly express FAP." (PMID 35608703, 2022). "Fibroblast activation protein (FAP; also known as seprase) is a surface‐expressed proteolytic enzyme that has been identified as a promising immunotherapy target antigen for epithelial carcinomas such as prostate, lung and pancreatic cancer, and mesothelioma." (PMID 33082953, 2020). "Moreover, a first‐in‐human clinical trial of FAP‐targeting CAR‐T cells has been launched in the setting of mesothelioma, with a first patient successfully infused." (PMID 33082953, 2020). "T cells expressing anti-FAP CARs at high level were generated by standard procedures and these re-directed T cells were antigen-specific as characterized by their specific in vitro killing of FAP positive mesothelioma cells." (PMID 23937772, 2013). "Additionally, FAP-specific re-directed T cells lysed FAP positive mesothelioma cells and inflammatory fibroblasts in an antigen-specific manner in vitro." (PMID 23937772, 2013). "Agents that inhibit FAP activity, anti-FAP antibodies, FAP-targeted vaccines, and CAR-T cell therapy have shown efficacy in depleting CAFs in preclinical models of malignancies such as mesothelioma." (PMID 40963620, 2025). "At present, one clinical trial has been conducted in mesothelioma patients to assess the safety and feasibility of local CAR T cell therapy targeting FAP on the mesothelioma cells." (PMID 37240052, 2023). "Overall survival (OS) analysis showed that high expression of FAP was significantly correlated with poor prognosis in adrenocortical carcinoma (ACC), COAD, GBM, HNSC, KIRP, brain lower grade glioma (LGG), and Mesothelioma (MESO)." (PMID 37166418, 2023). "Preliminary data using intrapleural FAP-targeted CAR T cells in mesothelioma showed redirected T cell activity in vitro with no significant toxicity; these data were later supported by a phase I clinical trial involving three mesothelioma patients." (PMID 34226685, 2021).
glioma (28 papers, 2010 to 2025). A benign or malignant brain and spinal cord tumor that arises from glial cells (astrocytes, oligodendrocytes, ependymal cells). "The utilization of MRI examination aids in the confirmation of the underlying cause responsible for the upregulation of FAP expression in gliomas." (PMID 37864148, 2023). "According to the literature, the FAP expression in grade 2 gliomas is generally lower than that of patients with grade 3 and grade 4 gliomas, indicating that high-grade gliomas are associated with a high level of FAP expression." (PMID 37864148, 2023). "Survival analysis in the large TCGA and CGGA datasets consistently showed that across gliomas of all malignancy grades, high-level tumor FAP mRNA was associated with poor prognosis with high statistical significance." (PMID 33308315, 2020). "Our data also confirms prior reports that expression of SNAI2 and FAP is directly linked to malignant glioma grade and further showed that they are coordinately upregulated in gliosarcoma, the grade IV glioma with the most overt mesenchymal differentiation." (PMID 20646316, 2010). "Increased FAP expression was associated with poor survival in glioma." (PMID 36382346, 2023). "FAP is produced by human cancer-associated fibroblasts (CAFs) in tumors such as glioma." (PMID 37864148, 2023). "In a chorioallantoic membrane assay, co-application of FAP+ mesenchymal cells with glioma cells was associated with enhanced abnormal angiogenesis, as evidenced by an increased number of erythrocytes in vessel-like structures and higher occurrence of haemorrhages." (PMID 34282761, 2021). "Recent studies have associated a high level of FAP expression with high-grade glioma." (PMID 34068501, 2021). "FAP was expressed at significantly higher levels in glioma lines than in carcinoma lines (P < 0.0001), in keeping with previous studies showing that FAP expression in carcinomas is limited to the cancer‐associated fibroblasts, rather than the tumor cells themselves." (PMID 33082953, 2020). "Compared to U87 glioma cells, FAP+ pericyte‐like cells and HBVP had 15–44 times higher abundance of collagen alpha‐1(I) chain, 16–31 times higher abundance of collagen alpha‐2(I) chain proteins, and 21–68 times higher abundance of FN1." (PMID 38705944, 2024). "To assess the effect of ECM produced by FAP+ pericyte‐like cells on glioma cell migration, we coated the bottom side of transwell inserts with solubilized ECM and performed a haptotaxis assay." (PMID 38705944, 2024). "Collectively, our results support the conclusion that FAP+ pericyte‐like cells contribute to glioma cell dissemination." (PMID 38705944, 2024). "The complex ECM produced by FAP+ pericyte‐like cells increased the migration of various glioma cell lines including GSC cultures." (PMID 38705944, 2024). "Increasing the number of low-grade gliomas, particularly those with low FAP expression, would likely reduce the sensitivity of 68Ga-FAPI-46 PET in diagnosing gliomas." (PMID 39629119, 2024). "FAP-positive cells in immunohistochemical tests are spindle-shaped, fibroblast-like cells, which is consistent with our findings in gliomas." (PMID 37864148, 2023). "The role of fibroblast activation protein (FAP) in gliomas has been demonstrated to facilitate tumor progression." (PMID 37864148, 2023). "Among the genes related to the EMT pathway, FAP was more highly expressed in GBM samples than in WHO grade II glioma samples (p < 0.05, Student's t‐test)." (PMID 36382346, 2023). "Distinct characteristics of serum FAP levels can be observed in various grades of gliomas, as determined by the molecular phenotype." (PMID 37864148, 2023). "A group of researchers have identified a notable elevation in FAP levels among patients diagnosed with glioma." (PMID 37864148, 2023). "This study seeks to evaluate the feasibility of glioma detection through the utilization of a serum FAP marker." (PMID 37864148, 2023).
glioma (continued). "Histopathological studies revealed that FAP expression was elevated in gliomas, particularly in mesenchymal subtypes." (PMID 37864148, 2023). "According to our findings, it has been observed that the utilization of serum-derived FAP obtained from patients diagnosed with glioma can serve as a viable method for disease detection." (PMID 37864148, 2023). "Another intriguing finding is that serum FAP level has a suggestive role in the molecular pathological subtypes of glioma." (PMID 37864148, 2023). "In relation to the 1p/19q codeletion, the serum FAP level was found to be higher in grade 2 glioma compared to grade 3 glioma (Fig. 1IIIe; P = 0.6583)." (PMID 37864148, 2023). "In this regard, it would be extremely interesting for future studies to continuously track gliomas using serum FAP." (PMID 37864148, 2023). "Due to the limited amount of research conducted on blood FAP for glioma trace, it is imperative to explore the potential of dynamic monitoring of tumor markers for clinical utilization." (PMID 37864148, 2023). "The findings revealed a notable elevation in serum FAP levels among the majority of high-grade gliomas." (PMID 37864148, 2023). "The promotion of posttreatment glioma invasive growth by FAP suggests the existence of actively proliferating tumor cells." (PMID 37864148, 2023). "In the present study, we conducted an investigation to identify the presence of the serum marker FAP and assess its viability as a means of monitoring the progression of glioma." (PMID 37864148, 2023). "The incorporation of serum-derived FAP obtained from glioma patients, in conjunction with MRI evaluation, substantially enhances the precision of disease diagnosis." (PMID 37864148, 2023). "The restricted expression profile of FAP in normal adult tissues and its overexpression in a variety of pathologies has intensified research efforts focused on the development of anti‐FAP therapies, but the role of FAP in gliomas has been poorly studied." (PMID 36382346, 2023). "In the present study, we conducted an analysis to determine the levels of FAP in the serum of patients diagnosed with glioma, and subsequently compared these levels with the assessments of tumor burden obtained through MRI imaging." (PMID 37864148, 2023). "SPECT applicable imaging probe, 99mTc-HYNIC-FAPI-04, was synthesized and evaluated in tumor cells and animal models of FAP-positive glioma and FAP-negative hepatoma, and then compared with 18F-FDG or 68Ga-FAPI-04 PET/CT." (PMID 36986521, 2023). "The levels of serum FAP were found to be lower in glioma patients exhibiting 1p/19q codeletion compared to those with 1p/19q non-deletion (Fig. 1IIId; P = 0.5272)." (PMID 37864148, 2023). "Multiple studies conducted on stromal cells, specifically CAFs, within gliomas have revealed the presence of FAP expression in neoplastic glial cells." (PMID 37864148, 2023). "A considerable proportion of gliomas exhibited a significantly increased level of serum autoantibody relative FAP level." (PMID 37864148, 2023). "Collectively, we conducted an investigation into the potential of serum-derived FAP obtained from patients with glioma to function as a biomarker for the disease." (PMID 37864148, 2023). "The serum FAP level was found to be higher in grade 4 glioma compared to grade 3 glioma among patients with MGMT unmethylation (P = 0.2604)." (PMID 37864148, 2023). "Patients with gliomas in the TCGA cohort were divided into two groups according to the expression level of FAP." (PMID 36382346, 2023). "Our study demonstrates serum FAP levels in preoperative gliomas are significantly higher than those in postoperative patients, suggesting a positive correlation between serum FAP levels and tumor burden." (PMID 37864148, 2023). "Based on our research findings, there exists a positive correlation between the level of serum FAP and both the grade and molecular state of glioma." (PMID 37864148, 2023).
glioma (continued). "We adopted enzyme-linked immunosorbent assay (ELISA) technique to quantify the relative FAP level of serum autoantibodies in a cohort of 87 gliomas." (PMID 37864148, 2023). "In order to ascertain the potential correlation between changes in serum FAP levels and the progression of glioma during treatment, a series of serum samples were collected from a cohort of 33 patients for the purpose of FAP analysis." (PMID 37864148, 2023). "This resulted in a significant decrease in FAP protein and FAP activity levels in the inhibitor-treated glioma cells providing evidence that autocrine/paracrine TGFbeta-1 signaling can contribute to the regulation of baseline FAP levels." (PMID 33494271, 2021). "Using ELISA, we confirmed FAP upregulation on the protein level in permanent glioma cell lines and endothelial cells." (PMID 33494271, 2021). "Nucleated avian red blood cells were identifiable in vessel-like structures and their quantity was higher in tumours containing FAP-expressing mesenchymal cells than in tumours formed from U87 glioma cells alone." (PMID 34282761, 2021). "In GBM, increased FAP expression has been detected mainly in mesenchymal stromal cells, astrocytes, glioma neural stem cells and sporadic CD45-positive cells." (PMID 34068501, 2021). "This supports the conclusion that TGFbeta signaling induces direct activation of FAP gene expression by pSmad complexes in glioma cells." (PMID 33494271, 2021). "Translational applications of FAPVap would require that the probe be able to sense physiological levels of FAP found on patient-derived glioma cells and that the vasoprobe-based contrast mechanism operates robustly in human subjects." (PMID 34931988, 2021). "Using in vitro and in vivo models, we further demonstrate that FAP+ mesenchymal cells induce endothelial cell migration and sprouting and stimulate the growth and migration of glioma cells by soluble mediators." (PMID 34282761, 2021). "FAP expression levels also differ among established glioma cell lines, indicating the utility of FAP measurements as a basis for characterizing brain tumors." (PMID 34931988, 2021). "This proline-specific protease is the closest FAP homologue and is co-expressed with FAP in some cell types including glioma cells." (PMID 33494271, 2021). "In glioma cells, this effect is mediated by the TGFbeta type I receptor and canonical Smad signaling and involves activation of FAP gene transcription." (PMID 33494271, 2021). "In cultured U87 and U251 glioma cell lines, we observed an accumulation of the secreted endogenous TGFbeta-1 in the culture medium and a parallel increase in the baseline FAP protein and FAP activity levels in the cells." (PMID 33494271, 2021). "Compared to control, the growth of glioma cells in the presence of FAP+ mesenchymal cells was higher." (PMID 34282761, 2021). "Recent studies have found that FAP expression in different types of cells within the GBM microenvironment is typically upregulated compared with that in lower grade glioma and is most pronounced in the mesenchymal subtype of GBM." (PMID 34068501, 2021). "The researchers discovered that some of the perivascular FAP+ cells more resembled tumor cells than pericytes; therefore, they were assumed to be glioma stem cells, which have been reported to preferentially reside in the perivascular niche." (PMID 34068501, 2021). "To assess the effect of FAP+ stromal cells on glioma cell growth, we co-cultured them with enhanced green fluorescence protein expressing glioma cells (U251eGFP)." (PMID 34282761, 2021). "Nevertheless, at a treatment concentration of 1 μM, both inhibitors completely prevented the TGFbeta-1-induced upregulation of FAP protein and FAP enzymatic activity in U87 glioma cells." (PMID 33494271, 2021). "This staining pattern is in line with the results of previous smaller studies showing FAP expression in glioma cells and in the stroma." (PMID 34282761, 2021).
glioma (continued). "Comparison of U138 FAP expression with literature reports indicates that several glioma cell lines derived from human tumors express higher FAP levels (e.g., U118, U343), while some others express less FAP (e.g., U87, U373)." (PMID 34931988, 2021). "In the chorioallantoic membrane GBM model, tumours containing FAP+ mesenchymal cells were more vascularised and developed haemorrhages more frequently than either glioma cells alone or glioma cells with admixture of human brain vascular pericytes (HBVP)." (PMID 34282761, 2021). "To better define the phenotypic characteristics of FAP+ cells in human glioma samples, we first used FAP/nestin and FAP/PDGFRβ double immunostaining on human glioma specimens." (PMID 33308315, 2020). "With respect to neuroepithelial cancers, Mentlein and colleagues, using quantitative reverse transcriptase PCR (RT-PCR) and immunohistochemistry, determined that FAP expression was elevated in several glioma subtypes." (PMID 32806623, 2020). "We first examined the expression of FAP and its potential role as a biomarker in human glioma using two large glioma datasets, TCGA and CGGA." (PMID 33308315, 2020). "Analysis of two published microarray datasets (GSE5016148 and GSE5002149) revealed that FAP gene expression was above normal brain levels in a variable proportion of tumor tissues for five distinct paediatric glioma types." (PMID 33082953, 2020). "We therefore also assessed FAP expression on a panel of 18 glioma neural stem (GNS) cell cultures, using flow cytometry." (PMID 33082953, 2020). "FAP transcripts were significantly higher in IDH-wildtype gliomas compared to IDH-mutant counterparts." (PMID 33308315, 2020). "Compared to normal brain controls, the mean TWIST1, SNAI2 and FAP expression were all up-regulated in the most malignant grade IV gliomas compared with grade II and III tumors (p = 0.022, p = 0.0014, p = 0.005, respectively)." (PMID 20646316, 2010). "The clinical relevance of identified putative TWIST1 targets was established through correlation between TWIST1, SNAI2 and FAP expression levels in 39 human gliomas of different grades." (PMID 20646316, 2010). "The highly correlated expression of TWIST1 and mesenchymal target genes SNAI2 and FAP in human gliomas supported the clinical relevance of TWIST1 mesenchymal change." (PMID 20646316, 2010). "In flow cytometry assays using U-87 MG human glioma cells expressing both FAP and LRRC15, the dual-targeted antibody demonstrated increased binding (EC50 = 0.2645 nM vs. 12.68 nM and 0.8885 nM) compared to the FAP-only mAb (EC50 = 12.68 nM) and LRRC15-only mAb (EC50 = 0.8885 nM) controls." (PMID 41228205, 2025). "This FAP-targeted tracer, engineered with a quinolinium-based scaffold, exhibited high tumor specificity, strong in vivo stability, and significant uptake in FAP-expressing glioma tumors, further supporting its theranostic potential in neuro-oncology." (PMID 40806525, 2025). "Additionally, given the involvement of the tumor microenvironment in gliomas, particularly the expression of fibroblast activation protein (FAP), the same radioisotope (68Ga) has been employed in the development of [68Ga] Ga-SMIC-3002." (PMID 40806525, 2025). "Preclinical and pilot studies have shown FAP expression in high-grade gliomas." (PMID 39759219, 2024). "In addition to COLI and FN1, several other ECM proteins were more abundant in the 3D extracellular matrices produced by FAP+ pericyte‐like cells compared to glioma cells." (PMID 38705944, 2024). "Therefore, we next selected a panel of patient‐derived glioma neural stem (GNS) cells as a more biologically relevant type of target cell to test the cytotoxic activity of our FAP‐CAR‐T cells." (PMID 38975278, 2024). "Alternatively, optimizing the physicochemical properties of FAP-targeted molecules to improve BBB penetration may enhance diagnostic accuracy and expand their applications in glioma diagnosis." (PMID 39629119, 2024).